ATF3 (activating transcription factor 3)
Diseases named in the same sentence as ATF3 in open-access papers (continued):
Sharing a sentence is not in itself a finding about the gene and the disease.
cancer (continued). "Furthermore, if miRNAs were globally reduced among cancer cells, then this would theoretically indicate the possibility of enhanced activity by ATF3 in such a system, which could exacerbate disproportionate protein expression." (PMID 26418018, 2015). "Finally, to determine whether the ATF3 was a target of cancer therapy, we treated the ESCC cells with Cisplatin, which is the most active antitumor agent used in human chemotherapy." (PMID 25149542, 2014). "A recent study using cancer cell lines reveals that the tumor metastasis suppressor gene, NDRG1, represses Wnt/β-catenin signaling by directly interacting with the Wnt receptor, LRP6, consequently causing the suppression of Wnt/β-catenin target gene, ATF3 expression." (PMID 23741453, 2013). "Targeting ATF3 expression through EENL could be a promising strategy for cancer therapy." (PMID 22461839, 2012). "Moreover, the question of how ATF3 induces proliferation of cancer cells remains unsolved." (PMID 21414204, 2011). "Further understanding of the switching mechanism of ATF3 function as a transcriptional activator or repressor might help develop strategies to selectively manipulate a subset of ATF3 target genes to assist the treatment of chemotherapy-resistant cancers." (PMID 22046379, 2011). "Importantly, and of high clinical relevance, we could show in the current and in one preliminary previous study that ATF3 expression can be induced in cancer cells by Hsp90 inhibition in vitro and in vivo." (PMID 21129190, 2010). "Consistent with mRNA expression, ATF3, HO1, CHAC1, and PTGS2 are significantly up-regulated in cancer cells after challenging with Fe-EGCG@RSL3." (PMID 40530387, 2025). "ATF3 and ATF4, belonging to the activating transcription factor (ATF) family, are involved in critical cancer biology pathways and mediate cellular responses to stress." (PMID 40722679, 2025). "Activating transcription factor 3 (ATF-3), a member of the ATF/CREB transcription factor family, primarily promotes the co-selection of cancer cells by the host and facilitates invasion and metastasis by regulating the host response." (PMID 40406488, 2025). "ATF3 has also been known to enhance EMT and invasion in various cancer types by upregulating several EMT and cell motility-related genes." (PMID 40016181, 2025). "Subsequently, cell-cell communication analysis unraveled that ATF3+CD8T cells and FTH1+NKT occupied most interactions with the cancer cells." (PMID 39238647, 2024). "Cancer-related genes such as CXCR4, MMP7, CDC20 and CDK6, and unfolded protein response (UPR)-related genes such as ATF3, ATF4, XBP1 and CHOP, showed significant differences in expression in the indicated cells." (PMID 38263248, 2024). "Activating transcription factor 3 (ATF3), an adaptive and stress response gene, is reported to be dysregulated in human cancers." (PMID 38300343, 2024). "All the other genes (ATF3, EMP1, GADD45B, SOCS3, and ZFP36), distinct from EGR3, have been independently demonstrated to function as migration inhibitors in cancer cells." (PMID 38543002, 2024). "Activating transcription factor 3 (ATF3) is an important ferroptosis inducer and targeting ATF3 offers a potential means to cancer therapy." (PMID 37580343, 2023). "Top up-regulated genes related to cancer were: (i) IL-20, CLK1, SORBS2, ERG1, PIM1, SNORD3A for normal FHC cells and (ii) TSLP, BHLHA15, LAMP3, ZNF27B, KRT17, ATF3 for cancerous HT29 cells." (PMID 38033043, 2023). "Our results showed that ATF3-mediated Tip60 upregulation and p-Foxo3a downregulation preceded SKOV-3 cancer cell apoptosis, suggesting that C. majus-induced SKOV-3 cell apoptosis was mediated by Foxo3a phosphorylation and dephosphorylation." (PMID 35283423, 2022).
cancer (continued). "Significantly, miR-494 was identified as a cancer-promoting gene in HCC 27-29, and ATF3 was significantly downregulated in HCC tissues in TCGA LIHC dataset." (PMID 35541917, 2022). "Dysregulation of ATF3, a cyclic AMP-dependent transcription factor, has been observed in diverse cancers, especially in various step of tumorigenesis." (PMID 35631574, 2022). "Of note, AREG, ATF3, DUSP1, and ZFP36 were all related to cancers or pathways in cancer, and numerous studies have reported a role for these genes in different tumors." (PMID 35372438, 2022). "In contrast to cancer cells, SCD1 inhibited the production of CCL4 by CD8+ T cells through increased ATF3 activated by ER stress." (PMID 35793868, 2022). "Since M2-skewed macrophages are immune suppressive (inhibiting cytotoxic immune cells from killing cancer cells), this pattern is consistent with the nature of these macrophages (Atf3+/+ from CTX-treated mice, group 2) as anti-apoptosis for cancer cells." (PMID 34298975, 2021). "Our finding that the antimicrobial CAMP peptide kills cancer cells is consistent with previous reports and suggests that adding CAMP is a potential way to counteract the pro-cancer effect of ATF3, thus improving chemotherapy." (PMID 34298975, 2021). "A recent study also reported that ATF3 and EGR1 are involved at the beginning of the inflammatory processes related to cancer." (PMID 34497759, 2021). "In the Atf3 KO lung, CTX also increased the ability of lung to retain cancer cells upon their arrival." (PMID 34298975, 2021). "In both cancer cells and mice tumors, the increase in ATF3 expression was accompanied with upregulation of GADD34, which is known as a downstream effector of ATF3 and induces apoptosis through inactivation of Akt signaling." (PMID 33801424, 2021). "Some studies showed that heat-shock protein 90 (Hsp90) inhibitor (17-DMAG) induces ATF3 expression in human gastric (TMK-1), colon (HT29, HCT116, SW620), and pancreatic (L3.6pl) cancer cell lines." (PMID 32922364, 2020). "Finally, we demonstrate that ATF3 acts as a master regulator of metabolic homeostasis and, therefore, may be an appealing target for the treatment of metabolic dyshomeostasis, immune disorders, and various cancers." (PMID 32922364, 2020). "Obtaining a better understanding of how ATF3 modulates metabolic, immuno-responsive, and oncogenic signaling pathways could pave the way for the transcription factor to become an intriguing target for the treatment of metabolic dyshomeostasis, immune disorders, and various cancers." (PMID 32922364, 2020). "While the basal SDF-1 levels are transcriptionally regulated by ATF3 and JDP2, the potentiation of SDF-1 secretion following co-culture with cancer cells is most likely controlled post-transcriptionally." (PMID 30670778, 2019). "ATF3 overexpression vector and shRNAs were transfected into HCC cancer cells to upregulate or downregulate ATF3 expression." (PMID 30376856, 2018). "Moreover, ATF3 directly affects NAG-1 transcription, and we also observed a high expression of ATF-3 in R182 cells by western blotting (data not shown), suggesting that ATF3 might modulate NAG-1-linked cancer progression and drug resistance." (PMID 27708225, 2016). "Among the genes upregulated in GFPHigh cells are cytokines (IL-6, IL-8, or TNF) and transcription factors (KLF6, ATF3, SNAI2) that have been previously related with cancer stemness, cellular plasticity, or both." (PMID 25414831, 2014).
cancer (continued). "Furthermore, ATF3 may play another critical function in host defense by regulating the delicate balance between proliferative and apoptotic signals that contribute to the development of cancer." (PMID 23028726, 2012). "However, the mechanism by which ATF3 promotes proliferation of cancer cells remained unknown." (PMID 21414204, 2011). "Alterations of the regulatory function of ATF3 is highlighted by our finding that ATF3 is required for both activation and repression of pro-apoptotic genes such as BBC3/PUMA and TNFRSF10B/DR5 in stress response and cancer." (PMID 22046379, 2011). "Activating transcription factor 3 (ATF3) is induced by a variety of stress and inflammatory conditions and is over-expressed in many kinds of cancer cells." (PMID 22046379, 2011). "By stabilizing ATF3 expression, CCDC86 potentially enhances the pro-tumorigenic signaling mediated by ATF3, offering a new perspective on the role of coiled-coil domain-containing proteins in cancer biology." (PMID 40837407, 2025). "Given the significant increase in ATF3 expression in response to FADS1 inhibition, we set out to further investigate the potential role of ATF3 in mediating the impact of FADS1 inhibition on cancer cell growth." (PMID 40121894, 2025). "We further provide evidence that FADS1 is essential for supporting cancer cell growth by protecting cancer cells from persistent ER stress, which is mediated by the PERK-ATF4 pathway with the involvement of a key transcription factor ATF3." (PMID 40121894, 2025). "SDC4high CSCs exhibited high expression of genes such as KLF6, ATF3, and CXCL2, with Kyoto Encyclopedia of Genes and Genomes (KEGG) enrichment analysis revealing their involvement in TNF signaling, MAPK signaling, apoptosis, and cancer development." (PMID 39107908, 2024). "More detailed investigations based on gastric SNU638 and colon HCT116 cancer cells revealed that KU induced endoplasmic reticulum (ER) stress with the elevation of intracellular Ca2+, ROS and ER stress markers, such as BIP, PERK, IRE1α, p-EIF2a, CHOP and ATF3." (PMID 39457512, 2024). "To discover ATF3-dependent therapeutic options for quiescent cancer cells, we further initiated a chemical screen using the mechanistic set provided by the National Institutes of Health (NCI), hoping to find a compound targeting cells expressing ATF3." (PMID 37833290, 2023). "Combined with findings from our current study, we speculate that AREG, ATF3, DUSP1, and ZFP36 may serve as a bridge between cancer and OSA." (PMID 35372438, 2022). "In particular, the expression of FOS, FOSB, and ATF3 did not correlate with the low HSF1 levels in these cancer types." (PMID 36010586, 2022). "ATF3 has been shown to be involved in oxidative stress, GSH metabolism and cancer." (PMID 36506541, 2022). "Numerous reports have shown that ATF3 and GADD45G play critical roles in cancer." (PMID 35684411, 2022). "In the Atf3 knockout (KO) lung, CTX also increased the ability of lung to retain cancer cells." (PMID 34298975, 2021). "Likewise, activating transcription factor 3 (ATF3) represses SLC7A11 expression by binding to the SLC7A11 promoter, boosting the sensitivity of cancer cells to ferroptosis." (PMID 33891303, 2021). "Microarray-derived transcription profiling experiments, corroborated by RT-qPCR, have demonstrated that the ONC upregulation of the transcription regulator, activating transcription factor 3 (ATF3), plays a central role in the key events elicited by this enzyme in ovarian treated cancer cells." (PMID 33435285, 2021). "The mRNA levels of DDIT3, pERK, and ATF3 were highly upregulated upon 6-AN treatment in H460 cancer cells; however, XBP1 was not." (PMID 34827081, 2021). "Since the same cancer cells (with Atf3) are injected, it means that Atf3 in non-cancer host cells—referred to as the host Atf3 below—is necessary for chemotherapy to efficiently enhance lung colonization." (PMID 34298975, 2021).
cancer (continued). "We note that CTX does not affect cancer cell extravasation but the genotype of Atf3 in macrophages does." (PMID 34298975, 2021). "With our current results of FOXP3-mediated ATF3 regulation, future studies are indeed necessary to explore the FOXP3 spliced isoforms in ATF3 regulation as well as the role of SRSF1 in FOXP3 isoform regulation, especially in the cancer field." (PMID 34768829, 2021). "Third, although Atf3 provides a protection against septic shock as evidenced by the lower rate of death in WT than Atf3 KO mice, Atf3 is not beneficial in the context of cancer and chemotherapy." (PMID 34298975, 2021). "Previous studies indicated that ROS could induce ATF3 expression and MLN4924 could induce ROS production in cancer cells." (PMID 32398095, 2020). "In the current study, FB traced tibial cavity neurons were not sensitised in the late stage cancer, which corresponds to the normalised Atf3 level in this group." (PMID 33172040, 2020). "Furthermore, ATF3 and JDP2 were found to regulate SDF-1 transcription and secretion in fibroblasts, a phenomenon that is potentiated in the presence of cancer cells." (PMID 30670778, 2019). "KLF6 has been reported to upregulate p21 and ATF3, but suppress PTTG1 expression in cancer cells." (PMID 28572744, 2017). "In contrast to astrocytes, ATF3 can function as a pro-apoptotic protein and mediate apoptosis by anti-cancer agents including nonsteroidal anti-inflammatory drugs (NSAID), conjugated linoleic acid, LY294002, curcumin, and 3,3’-diindolylmethane in cancer cells." (PMID 27043582, 2016). "For instance, DDIT3 (C/EBP homology protein (CHOP)) and ATF3 are markedly upregulated in response to ATF4 activation, particularly under prolonged stress conditions, which eventually leads to cell death in normal as well as cancer cells." (PMID 26657730, 2016). "ATF3 up-regulates the genes TWIST1, fibronectin (FN)-1, SNAIL and SLUG in MCF10A cancer cells." (PMID 26537518, 2015). "Overexpression of ATF3 increased CCND1/2 expression in PC3 and DU145 cancer cells." (PMID 23591848, 2013). "Atf3 J1 and J3, the two isoforms with the lowest expression in DRG neurons, use the P1 promoter which is primarily active in response to stress and in numerous cancers, whereas the conventional Atf3 promoter (P2) typically is reactive to mitogenic stimuli." (PMID 22272348, 2012). "At 14 days of cancer development, ATF-3 reactivity was absent in sham and contralateral sensory neurons." (PMID 21048940, 2010). "To address the role of MAPKinases, we employed specific inhibitors to these pathways in a cancer cell line panel and found no consistent inhibition of M344 mediated ATF3 induction." (PMID 20828393, 2010). "The up-regulation and down-regulation of genes in the cancer cells could also be attributed to the activation of specific transcription factors such as ATF3, RUNX2, ERG, DLX1 (and DLX2) identified in the cancer cell transcriptomes." (PMID 20021671, 2009). "Not so many ATF3 downstream targets in the context of cancer are known." (PMID 38658567, 2024). "As high expression levels of ATF3 are a feature of QCCs that promotes resistance to anticancer reagents in CRC cells, we asked whether lowering ATF3 could improve the efficacy of drugs targeting the proliferating cancer cells." (PMID 37833290, 2023).
cancer (continued). "Finally, to obtain further insights into potentially relevant mechanisms in OSA pathogenesis, we used GSEA to analyze the signaling pathways related to AREG, ATF3, ZFP36, and DUSP1, and found that all four markers were related to inflammation and cancer-related pathways." (PMID 35372438, 2022). "It is currently unknown whether ATF3 contributes to the generation or specialization of the cancer stem cells in human cancers nor the maintenance or self-renewal of the normal stem cells." (PMID 35052581, 2021). "Our search for mechanisms underlying the induction of HLA-G showed that both HHV-6A/6B infection and U94 transfection/protein treatment are potently upregulating ATF3, which so far was known to be involved in immune response, inflammation and cancer, but not in HLA-G induction." (PMID 30523283, 2018). "Since immune dysfunction plays a critical role in promoting metastasis, this may explain the value of stromal, but not cancer, Atf3 to predict outcome." (PMID 30373101, 2018). "It is not clear how ATF3 acts in a dichotomous nature in cancer development." (PMID 28860159, 2017). "Our results suggested that the protein level and activity of MMP-2, a Type IV collagenase which was critical in cancer cell invasion and metastasis, was attenuated in the ATF3-expressing cells, suggesting that MMP-2 might be a downstream molecule of ATF3 function." (PMID 25149542, 2014). "Therefore, Atf3 in macrophages, but not ECs, affected cancer cell transendothelial migration." (PMID 34298975, 2021). "Though FOXP3 has an essential and critical role in autoimmunity, cancer development, and Treg development, with hundreds of FOXP3 target genes already identified in both cancer cells and Treg cells, the functional role of FOXP3 in regulating ATF3 is largely unknown." (PMID 34768829, 2021). "A similar effect occurs for the ectopic overexpression of ATF3 that, in several types of cancer, promotes CAF proliferation and in parallel the growth of adjacent cancer cell lines in a non-cell autonomous manner." (PMID 38124183, 2023). "CHOP and DR5 were not enhanced in ATF3- and ATF4-depleted cancer cells treated with bortezomib, a proteasome inhibitor." (PMID 26188905, 2015). "Unlike normal prostate tissue and androgen-responsive LNCaP cancer cells, androgen-independent PC3 and DU145 cancer cells did not express ATF3 endogenously." (PMID 23591848, 2013). "For the nine added TF genes, seven of them were reported to take part in apoptosis in various types of cancer or diseases; these seven TFs are STAT3, ETS1, LEF1, STAT4, E2F3, ATF3, and HMGA2, which have not been annotated by GO yet." (PMID 22952919, 2012). "However, it failed to block the induction of ATF4, ATF3, CHOP, GADD34, and TRIB3 proteins induced by DT-061 treatment in cancer cells." (PMID 39349971, 2024). "However, no or weak levels of ATF3 were expressed in PC3 and DU145, two androgen-independent cancer cells." (PMID 23591848, 2013).